MSH5-SAPCD1 (MSH5-SAPCD1 readthrough (NMD candidate))
Synonyms: MSH5-C6orf26
Gene: Protein-coding gene on chromosome 6 (31,740,020 to 31,764,851, forward strand). Ensembl gene ENSG00000255152.
Genetic constraint (gnomAD): Missense variants: 906 observed, 1,100.5 expected, observed/expected ratio (o/e) 0.82, 90% interval 0.78 to 0.87. Synonymous variants: 336 observed, 422.78 expected, observed/expected ratio (o/e) 0.79, 90% interval 0.73 to 0.87.